APC (APC regulator of Wnt signaling pathway)
Diseases named in the same sentence as APC in open-access papers (continued):
Sharing a sentence is not in itself a finding about the gene and the disease.
cancer (continued). "For example, the MYC locus in SW480 cells contains 135 rearrangements in a 4-Mb genomic window, whereas a larger complex event was observed in HCC1954 cells around the similar locus, which also involved two other cancer driver genes, TERT and APC, on chromosome 5." (PMID 32024999, 2020). "In the nucleus, WTX, β-catenin, β-TrCP2, APC and AXIN1 form a new complex, and this complex could inhibit the cancer process by promoting the degradation and ubiquitination of β-catenin protein and down regulating Wnt signaling." (PMID 30939162, 2019). "It is clear from the genetic data that there are individuals present in the UK10K cohort who have cancer syndromes caused by deleterious mutations (such as BRCA1 nonsense, BRCA2 frameshift and APC frameshift variants)." (PMID 29641532, 2018). "From the seven most promising candidates, six (APC, CCND2, FOXA1, PSAT1, RASSF1A and SCGB3A1) confirmed its cancer-specificity, discriminating normal from cancerous tissues, although with variable performance, paralleling previous observations from our team and others." (PMID 30405052, 2018). "APC and CTNNB1 also displayed predominantly negative associations in two different cancer types each." (PMID 29125844, 2017). "The observed mutation frequencies are in concordance with published data, taking into account that the TruSeq Amplicon Cancer Panel (TSACP) targeted massive parallel sequencing approach did not cover the complete APC gene." (PMID 27729614, 2016). "Together, these data support the general notion that cell intrinsic reduction of canonical WNT signaling responses in cancer cells is pro-metastastic, and argue that the status of APC is not simply correlated to the outcome of modulation of WNT-TCF signaling." (PMID 26939070, 2016). "Twenty-four (63.2 %) of the 38 cancers were copy number neutral, and 14 (36.8 %) were not copy number neutral, at the loci of the APC gene studied." (PMID 26970738, 2016). "In contrast, deletion of the APC locus on chromosome 5q did not significantly differ in carcinomas compared to polyps." (PMID 27329586, 2016). "DNA bisulfite sequencing of these cloned fragments showed that nearly all CpG dinucleotides were methylated in LNCaP and/or PC-3 cancer cell lines, but not in benign cell lines and blood (illustrated in Figure A in S1 File for APC)." (PMID 26086362, 2015). "Hypermethylation of APC, CCND2, GSTP1, PTGS2 and RARB was highly cancer-specific." (PMID 26086362, 2015). "Nevertheless, in cancer cells lacking APC destruction complex function (e.g. lacking APC), the overall effect of enhancing PP2A function via Ivermectin treatment is predicted to be pathway silencing (Fig6H)." (PMID 25143352, 2014).
cancer (continued). "Although APC protein has been shown to be genetically or epigenetically inactivated in a variety of carcinomas, some authors have reported that they have not detected alterations of the APC gene in samples of myxoid/round-cell LS examined." (PMID 25024863, 2014). "A previous study focusing on DNA methylation profiles in HCC at a few selected loci of tumor suppressor genes and oncogenes found methylation changes in the promoters of 9 cancer-related genes, including SOCS-1, GSTP, APC, E-cadherin, RAR-beta, p14, p15, p16 (CDKN2A), and p73." (PMID 23437062, 2013). "Among nine cancer-associated mutations that determine sensitivity to ATRA (Notch 1, BCR_ABL, KIT, FLT3, APC, TET2, K-ras, ALK, MLL_AFF1), KRAS, APC, and KIT mutations are associated with resistance to ATRA (only K-ras is shown)." (PMID 23982413, 2013). "The APC promoter was hypermethylated in 15 out of 27 cancer samples and in none of the control samples." (PMID 23431474, 2013). "Hypermethylation at the APC promoter was observed in 58% (i.e., 15 out of 27) of the cancer cases but in none of the benign prostatic tissues." (PMID 23431474, 2013). "Another potential problem is that blood as a remote medium is not organ-specific; loci that are methylated in lung cancer may be methylated as well in other cancers, for example TNFRSF10C and D TCF21, RUNX3, APC, FBN2." (PMID 18947422, 2008). "In this study, we found that the presence of methylated APC or unmethylated E-cadherin in the pretherapeutic serum of cancer patients tended to have a nonsignificant trend towards poor survival." (PMID 15942635, 2005). "Mutation types in the APC gene differed significantly between PG and NPG carcinomas (P=0.0189), including frameshift mutations in 66% of PG carcinomas but no NPG carcinomas." (PMID 15213719, 2004). "_ConfirmMDx® (MDxHealth, Irvine, CA, USA): this is an epigenetic assay, measuring the DNA methylation status of three genes—glutathione-S-transferase P1 (GSTP1), adenomatous polyposis coli (APC), and Ras association domain-containing protein 1 (RASSF1)—in prostate biopsy tissue without cancer." (PMID 40863429, 2025). "First, the association between APC knockdown and 3' UTR lengthening in organoids is clearly evident for transcripts containing enriched motifs identified via motif enrichment analyses in primary human cancer samples but not when this restriction is removed." (PMID 39375704, 2024). "Recently, suppression of Anaphase-Promoting Complex/Cyclosome-Cell Division Cycle 20 (APC/C-CDC20) activity using CRISPR/Cas9 mutagenesis has been reported to increase sensitivity to Kinesin Family 18a (KIF18a) inhibition, which functions to suppress multipolar mitotic spindles in cancer cells." (PMID 38928036, 2024). "However, the specific relationship between the APC gene and various cancers and the mechanism of action are not understood." (PMID 35303016, 2022). "Overall, 586/7624 (7.6%) AJ with any cancer carried the I1307K APC variant compared to 342/4918 (6.9%) in the AJ control group (p = NS); however, among AJ males with any cancer, the rate of I1307K APC was significantly higher than in AJ males without cancer [OR 1.32 (95% CI 1.05–1.66), p < 0.05]." (PMID 36497357, 2022). "Moreover, BRAF mutated cancers with and without PIK3CA mutations are characterized by the absence of KRAS mutations and a lower prevalence of APC mutations than BRAF wild type counterparts." (PMID 36079062, 2022). "First, TBRG1, PICH1, NBL1, TRIM13 and APC did not impact gene up-expression in cancer." (PMID 33580150, 2021).
cancer (continued). "At stage 3, however, all these 26 defined TS genes have S > 0, suggesting that all these 26 TS genes had larger positive network effects on gene down-expression in cancer than negative network effects on gene up-expression even though APC, EXT1 and DDX5 had very small S-scores." (PMID 33580150, 2021). "For example, adenomatous polyposis coli (APC) promoter methylation could be a biomarker for early diagnosis of prostate cancer, and O6-methylguanine-DNA-methyltransferase (MGMT) promoter methylation might be a predictive biomarker for cancer prognosis." (PMID 31590287, 2019). "In six genes (p16, RASSF1A, GSTP1, APC, p15 and SFRP1), there was significant difference in the level of hypermethylation between HBV-positive carcinoma tissues and HBV-negative carcinoma tissues, revealing that HBV infection could induce methylation of these genes in HCC." (PMID 31772678, 2019). "Since APC, FOXA1 and RASSF1A were biomarkers common to BrC, CRC and LC, they were further tested as gene panel for cancer detection (designated “PanCancer”), whereas RARβ2, SCGB3A1, SEPT9 and SOX17 were considered a gene panel for discrimination of primary cancer localization (“CancerType” panel)." (PMID 30261643, 2018). "Six APC carriers developed extracolonic cancers with or without CRC." (PMID 28533537, 2017). "Besides, other studies have identified genes with significantly different methylation between different subtypes, and the differentially methylated genes (including CDKN2A, APC, CDH13, THBS2 and ERG) have been utilized to distinguish these different histological subtypes of cancers." (PMID 26862903, 2016). "Our results show that the mean of CTNNB1's GPVs in the APC mutant cell lines is 20% of that in the APC wild-type cell lines (P value <10–7), and CTNNB1 has significantly higher level of expression in APC mutant cancer cell lines than in wide-type cell lines (P value = 0.015, fold-change = 1.52)." (PMID 26937901, 2016). "The results of Egger’s test on APC promoter hypermethylation indicated that there was not obvious evidence of publication bias in the comparison of cancer and control groups, in relation to tumor grade, tumor stage, and tumor histology in cancer (all P > 0.05)." (PMID 27670526, 2016). "Among the ten genes, five of the TSGs (ATM, APC, BRCA2, NF1, and PTEN) were annotated with positive effects on apoptosis; the other three TSGs (PEG3, SPARC, and RPS6KA2) were also reported to increase apoptosis in sporadic epithelial OVC or other types of cancer." (PMID 22952919, 2012). "Thus, the APC/MCC pair provided an excellent example to showcase our cross-species comparison strategy, utilizing the difference in the genomic location of orthologous genes in different species to distinguish between cancer driver and passenger alterations." (PMID 20707908, 2010). "In addition, APC and the wingless-related integration site (WNT)/B-catenin pathways also serve to regulate COX-2 in a similar manner to NO, suggesting that NO may work in synchrony with COX-2 to promote its pro-cancer effects." (PMID 33513777, 2021). "Two major mechanisms that contributed to metastasis, one is APC methylation frequenly occurs early in breast cancer and increases during disease progression and the other one is that ‘de novo’ occur in the metastatic cancer cells even in lacking of methylation in the primary cancer cells." (PMID 33369461, 2020). "Here, we have shown that within cancers that bear BRAF mutation, the mutually exclusive nature of mutations in these genes remain, indicating that the mutual exclusivity is likely between APC and RNF43 mutations, rather than between BRAF mutations and APC mutations." (PMID 32384699, 2020).
cancer (continued). "The reduction of elevated RAS protein levels caused by APC and KRAS mutations might be an ideal therapeutic strategy that can target both CSCs and non-CSC cancer cells that have the potential to dedifferentiate into CSCs, without causing toxicity to healthy stem cells." (PMID 31362761, 2019). "In addition, APC and SMAD4 mutations have not been reported in this subtype of cancer either." (PMID 29133385, 2018). "Finally, VIMENTIN, which also appeared dysregulated in the APC mut HIO (logCPM 9.32429, p-value 1.59E-30 and FDR 4.42E-28) is overexpressed in several cancers including gastrointestinal cancers and correlates with poor prognosis and accelerated growth and invasion of cancer cells." (PMID 30024920, 2018). "While it is established that cell-cell junction proteins, such as E-cadherin, β-catenin, APC, and p120ctn, are involved in cell adhesion and motility as well as cancer cell growth, it is not clear whether δ-catenin overexpression exerts any effects on prostate cancer cells." (PMID 19284555, 2009). "Among these proteins, MME, CDH1, APC, and CA9 have not been previously reported to be involved in anti-cancer regulations." (PMID 41567641, 2025). "Hence, to effectively reactivate APC/CCDH1 E3 ligase activity in cancer via inhibiting negative regulators, activating positive regulators, or both, might hold promise as a potential therapeutic approach to induce the degradation of a group of crucial mitotic regulators that promote oncogenesis." (PMID 38622115, 2024). "In line with the oncogene‐induced DNA damage model for cancer development, this suggests that exercise may not have prevented the initial formation of DNA DSBs, although we cannot rule out that signalling pathways downstream of other oncogenes (eg, APC) were not altered by exercise." (PMID 35213038, 2022). "Surprisingly, in carcinoma cell lines of acquired doxorubicin resistance (MCF-7_ADR, NCI/ADR-RES), methylation of CGIs from APC, HIC1 and RASSF1 was strongly reduced or completely absent." (PMID 20544021, 2010). "GSTP1, RARB2, APC, and RASSF1A were each hypermethylated in 70–80% of carcinoma tissues, whereas the order in noncarcinoma tissues was RASSF1A>APC>GSTP1=RARB2." (PMID 15292941, 2004). "Furthermore, unlike CRC and other cancers, the WNT–MYC module is uncoupled in the liver and Myc deletion does not rescue the acute effects of APC loss." (PMID 41413654, 2026). "There is currently one validated epigenetic test commercially available, ConfirmMDx (MDxHealth, Irvine, CA, USA), designed for diagnostic rather than prognostic purposes, that uses the methylation profile of three genes (APC, RASSF1, GSTP1) to detect cancer in histologically negative biopsies." (PMID 33076494, 2020). "At the present time, APC is not directly druggable, and approaches aimed at targeting the upstream components of the WNT/β-catenin pathway would have minimal effect in APC-mutant cancers." (PMID 29895949, 2018). "Similarly to BRAF mutant/MSI cancers, BRAF mutant/MSS cancers do not typically truncate APC but still show moderately frequent activation of the Wnt pathway." (PMID 30598662, 2018). "As these genes besides APC, KRAS and SMAD4 are listed in neither of the cancer Census Genes nor the COSMIC CRC genes, they might be passenger mutations or HGCA-specific mutations that might not play an important role in HGCA progression to CRC." (PMID 28179590, 2017).
cancer (continued). "We found that the expression levels of the genes in the Wnt/β-catenin signaling pathway, including APC, β-catenin, TCF7L1, TCF7L2, LEF1, MMP7, C-myc, C-jun, CYCLIND1 and GSK-3β, were remarkably higher in cancer than non-cancer tissues in the p.1125Val>Ala mutant FAP family members." (PMID 29050326, 2017).